NRG1 (neuregulin 1)
Diseases named in the same sentence as NRG1 in open-access papers (continued):
Sharing a sentence is not in itself a finding about the gene and the disease.
schizophrenia (continued). "The neuregulin 1 (NRG1) gene is located on chromosome 8p12, and its role as a susceptibility gene for schizophrenia may be explained by the variety of processes of neuronal development and function that it modulates." (PMID 39518545, 2024). "Data suggest that NRG1-erbB4 is a signaling pathway of particular importance in schizophrenia." (PMID 39062492, 2024). "Furthermore, changes in NRG1 isoform expression levels in the post-mortem pre-frontal cortex of patients with major psychiatric disorders such as schizophrenia and unipolar depression have been consistently reported." (PMID 37583471, 2023). "NRG1 regulates both excitatory and inhibitory synaptic transmission in the adult brain, and abnormal neurotransmission and/or synaptic plasticity have been reported in both glutamatergic and GABAergic pathways in the brain of schizophrenia patients." (PMID 36980961, 2023). "Furthermore, another mechanism of NRG1/ErbB4 interactions to promote dendrite growth in mature interneurons is mediated by Kal7, whose encoding gene KALRN has been associated with schizophrenia." (PMID 36831241, 2023). "Neuregulin-1 (NRG1) is a paracrine growth factor and has been involved in synaptic plasticity and neural development, and plays a vital role in psychiatric diseases, such as bipolar disorder, schizophrenia, and depression." (PMID 37061663, 2023). "Different degrees of genetic variations or differences in the subtypes of patients with schizophrenia may also have contributed to the discrepancies in the reported serum NRG1 levels." (PMID 35337293, 2022). "Based on our data in this putative animal model for schizophrenia-like phenotype, we speculate that at least some of the sensorimotor gating deficits in schizophrenia patients may be due to reduction in NRG-1 in the PFC." (PMID 36620856, 2022). "Genetic variation in NRG1 has also been associated with hippocampal volume reductions in Icelandic patients with schizophrenia and in nonaffected family members." (PMID 35337293, 2022). "Abnormal Nrg1 expression has been observed in schizophrenia in clinical studies." (PMID 35562880, 2022). "Here we sought to determine if CBD given in adolescence could prevent the development of the schizophrenia-relevant phenotype, as well as susceptibility to the psychoactive cannabinoid Δ9-tetrahydrocannabinol (THC) in Nrg1 TM HET mice." (PMID 36406747, 2022). "Postmortem study has showed that cortical NRG-1 level is decreased in schizophrenia patients." (PMID 36620856, 2022). "Therefore, ctoNrg1 mice are a relatively better model for mimicking high levels of NRG1 in the etiopathology of schizophrenia." (PMID 35682647, 2022). "Neuregulin1 (NRG1) plays a role in neuronal migration, regulation of synaptic plasticity, and neural survival, and has been considered to be among the candidate genes for schizophrenia." (PMID 35337293, 2022). "We propose that mPFC NRG1 knockdown could be a suitable therapy for alleviating schizophrenia behaviors in FGR." (PMID 36460658, 2022). "Neuregulin 1 (nrg1), a substrate of BACE1, is a pre‐synaptic protein thought to be implicated in a number of neurodegenerative diseases and psychiatric/neurodevelopmental disorders such as AD, attention deficit hyperactive disorder (ADHD) and schizophrenia." (PMID 35338546, 2022). "Indeed, acute Nrg1 treatment has been found to increase GAD67 protein levels in a ketamine rat model of schizophrenia." (PMID 36406747, 2022). "An increasing body of evidence suggests that variation in genes that control the development and maturation of PV interneurons such as NRG1-ErbB4 signaling, DISC1, GRIN1 and DTNBP1, might confer susceptibility to schizophrenia." (PMID 36460658, 2022). "NRG1 knockdown in mPFC significantly rescues schizophrenia behaviors in FGR mouse." (PMID 36460658, 2022). "Besides, our results also demonstrated that mPFC NRG1 knockdown rescued FGR induced schizophrenia symptoms by improving GABAergic maturation of PV interneurons." (PMID 36460658, 2022).
schizophrenia (continued). "Altered NRG1/ErbB4 signaling has been shown to contribute to NMDAR hypofunction in patients with schizophrenia and mice with NRG1 deletion have 16% fewer functional NMDAR than wild-type mice, whereas if a similar change occurs also in ErbB4 KO mice was not determined." (PMID 34899420, 2021). "These increases could be caused by genetic factors, such as schizophrenia-linked single nucleotide-polymorphisms (SNPs) SNP8NRG221132 and SNP8NRG243177, which are identified to increase the mRNA levels of NRG1." (PMID 34725188, 2021). "Studies have identified several candidate loci on different chromosomal regions that may be associated with the risk of schizophrenia, including NOSAP1 (1q), RGS4 (1q), DNTBP1 (6p), NRG1 (8p), and G72/G30 (13q)." (PMID 34502372, 2021). "Visibly, NRG3 follows NRG1 into the spotlight of schizophrenia research, showing that the influence of genetic variation may exert on the specificity of a phenotype in addition to the risk for this disease." (PMID 33897409, 2021). "Furthermore, clinical and animal studies indicate a critical role of NRG-1 in the development of schizophrenia." (PMID 33708250, 2021). "To mimic increased Nrg1 expression in GABAergic interneurons from schizophrenia patients, we generated gtoNrg1 mice in which Nrg1 overexpression specifically occurred in GABAergic interneurons and could be turned off by doxycycline (Dox)." (PMID 33436636, 2021). "In the postmortem brains of schizophrenia, expression of NRG1 mRNA and protein was upregulated." (PMID 31653237, 2019). "In our schizophrenia-like model mice, it is unclear whether cell loss and NMDAR hypofunction occurs, although there is evidence for reduced NMDAR activation by NRG1 stimulation in the PFC of both human schizophrenia patients and rodent models." (PMID 31653237, 2019). "Consistent with this hypothesis, by examining the association between Neuregulin 1 gene (NRG1) and creativity, Kéri (2010) investigated for the first time the association between schizophrenia risk variants and creativity in healthy subjects." (PMID 31649580, 2019). "Another NRG1 heterozygous mice were generated by targeted disruption of type III NRG1, which is one of many NRG1 isoforms highly expressed throughout embryonic and postnatal brain development and are implicated in schizophrenia." (PMID 31417356, 2019). "Thus, our study both provides new insight into the role of NRG1 on synaptic function and behavior and provides a new approach for in vivo modeling of certain schizophrenia-like phenotypes." (PMID 29844389, 2018). "MK-801 can induce obvious schizophrenia-like behaviors while also decreasing NRG1 in the mouse." (PMID 30574102, 2018). "Based on the data reviewed above, we hypothesized that DMS could improve schizophrenia-like behaviors in mice through acting on myelinated white matter tracts, and the molecular mechanism might involve the regulation of NRG1 signaling." (PMID 30574102, 2018). "We did this by examining two schizophrenia-relevant brain regions across postnatal development (i.e., the prelimbic cortex and the hippocampus) in an established mouse model for schizophrenia, the heterozygous transmembrane domain Nrg1 mutant mice (Nrg1 TM HET)." (PMID 29467679, 2018). "In addition, several susceptibility genes for schizophrenia (e.g., DISC1, NRG1/ErbB4, and CRMP2), which are involved in either pre-synaptic DA release or post-synaptic D1R-related cascades, are similarly dysregulated by METH." (PMID 30061532, 2018). "These contradictory results could be explained by differences in the actual NRG1 and ErbB4 levels between early and late phases of schizophrenia, the severity of disease and the tissues sampled." (PMID 30574102, 2018). "Nrg1α-induced PI3K signaling is also impaired in lymphoblastoid cell lines derived from schizophrenia patients, suggesting PI3K-Akt-mTOR signaling in response to Nrg1 may be impaired in schizophrenia in a manner that mirrors the effects of reduced miR-137." (PMID 30618607, 2018).
schizophrenia (continued). "Reduced NRG1-ErbB4 signaling was also found in patients with first-episode schizophrenia." (PMID 30574102, 2018). "Signaling deficits in NRG1/ErbB3 has been identified in schizophrenia patients." (PMID 30319362, 2018). "Anti-NRG1 treated mice display behavioral changes that include tremor, recoverable alterations in motor function, as well as hyperlocomotion and impaired sensorimotor gating, which are both reported phenotypes in animal models of schizophrenia." (PMID 29844389, 2018). "In addition to providing insight into the role of NRG1 processing in CNS function, our results describe a novel model with relevant phenotypes for studying pathophysiological processes of schizophrenia." (PMID 29844389, 2018). "NRG1 and its cognate receptor ErbB4 regulate the development of activity-driven glutamatergic synapse development, indicating that NRG1 signalling may contribute to schizophrenia pathophysiology in the context of the glutamate hypothesis of schizophrenia." (PMID 29467679, 2018). "The regulation of Glu2B phosphorylation by NRG1 in both schizophrenia and symptomatic epilepsy may therefore provide some insights into the comorbidity between the two diseases." (PMID 28273943, 2017). "Recent studies have shown that Neuregulin-1 (Nrg1) is a candidate gene for schizophrenia." (PMID 28993723, 2017). "Ppy-DBSA combined with electrical stimulation may therefore correct impaired neurite growth arising from gene dysregulation relevant to schizophrenia, such as NRG1 and DISC1 haploinsufficiency." (PMID 28198409, 2017). "Across 2 different sites and protocols, Nrg1 mutants demonstrated deficits in prepulse inhibition, a measure of sensorimotor gating, that is, disrupted in schizophrenia; these deficits were partially reversed by acute treatment with second, but not first-, generation antipsychotic drugs." (PMID 28338897, 2017). "Since most studies have compared the total Nrg1 levels between schizophrenia and healthy controls, it is critical to know whether the specific activity of BACE1 in cleavage of Nrg1 plays an important role in schizophrenia." (PMID 28993723, 2017). "A critical question that emerges from these studies is whether altered Nrg1 signaling contributes to the glutamatergic hypofunction seen in patients with schizophrenia and/or psychoses and, if so, how." (PMID 28275713, 2017). "Using association analysis method, one study showed variants in NRG1 (rs2919381) and ERBB4 might contribute to susceptibility to schizophrenia in Japanese population." (PMID 28993723, 2017). "This suggests our findings, if extended, may contribute to a unique NRG1 mRNA alteration (signature) in the blood of individuals with schizophrenia or more specifically treatment-resistant schizophrenia." (PMID 29225331, 2017). "In contrast, the genetic studies of NRG1 in schizophrenia have been extensively investigated." (PMID 28993723, 2017). "A clinical study in Chinese Han patients indicated that exposure to risperidone and quetiapine for 4 weeks could increase the NRG1 expression of peripheral blood lymphocytes of first episode schizophrenia." (PMID 28993723, 2017). "While the underlying mechanisms involving NRG1 genotype in PPI are unknown, studies implicated that Nrg1 regulates NMDA receptors in specific brain regions that could induce PPI reduction and contribute to schizophrenia-like symptoms." (PMID 28993723, 2017). "Although there is considerable genetic and pathologic evidence for an association between neuregulin 1 (NRG1) dysregulation and schizophrenia, the underlying molecular and cellular mechanisms remain unclear." (PMID 28338897, 2017). "Importantly, Nrg1 and Nrg1/ErbB signaling regulate several processes of neurodevelopment that play extremely critical roles in schizophrenia neuropathology." (PMID 28993723, 2017).
schizophrenia (continued). "We found elevated levels of NRG1 mRNA, specifically the EGFα (P = 0.0175), EGFβ (P = 0.002) and type I(Ig2) (P = 0.023) containing transcripts, but lower NRG1-β1 serum protein levels (P = 0.019) in schizophrenia patients compared to healthy controls." (PMID 29225331, 2017). "Collectively, these studies suggest NRG1 may be dysregulated in brain and blood at both the mRNA and protein level in schizophrenia and flag peripheral blood as a potential surrogate for brain NRG1 dysregulation." (PMID 29225331, 2017). "An analysis of the statistical epistatic network of NRG1 in clinical studies of schizophrenia indicated its relationship with IL-1β16, which may be an important link to TLR signaling." (PMID 28646138, 2017). "It is suggested that only measuring BACE1 protein levels in the brain might not be sufficient to show BACE1-specific activity in cleaving NRG1 in schizophrenia." (PMID 28993723, 2017). "Additionally, animal models of overexpression with different Nrg1 isoforms also developed schizophrenia-liked behaviors." (PMID 28993723, 2017). "Meta-analysis have been performed to attempt to uncover the genes associated with schizophrenia, and many risk factor molecules, such as the NMDA receptor subunit 1 and 2A (NR1 and NR2A), disrupted in schizophrenia 1 (DISC1), neuregulin 1 (NRG1), dysbindin, and reelin have been proposed." (PMID 28870209, 2017). "TLR4 stimulation resulted in lower pro-inflammatory cytokine production in schizophrenia compared to the control levels, whereas the stimulation of ErbB by neuregulin 1 led to higher pro-inflammatory cytokine levels in patients with schizophrenia relative to the control group." (PMID 28646138, 2017). "This suggests a weakened NRG1-dependent anti-inflammatory response in schizophrenia." (PMID 28646138, 2017). "However, we have also expanded on this by showing NRG1 mRNA isoforms EGFα, EGFβ, and type I(Ig2) are elevated in whole blood of clozapine-treated schizophrenia patients." (PMID 29225331, 2017). "Numerous lines of evidence support the hypothesis that Nrg1 can contribute to the pathophysiology of schizophrenia." (PMID 28993723, 2017). "Nevertheless, two genes associated with schizophrenia, AKT1 and neuregulin 1 (NRG1), may also play roles in systemic metabolic regulation." (PMID 28804444, 2017). "In this study, we examined 12 NRG1 SNPs, eight NRG1 mRNA isoforms (type I, type I(Ig2), type II, type III, type IV, EGFα, EGFβ, pan-NRG1) in whole blood, and NRG1-β1 protein in serum of clozapine-treated schizophrenia patients (N = 71) and healthy controls (N = 57)." (PMID 29225331, 2017). "The role of NRG-1 in antioxidant and Cbl metabolism identified in this study may contribute to the etiology of schizophrenia and recognition of this mechanism may lead to novel treatment approaches." (PMID 27057274, 2016). "In addition to known involvement of NRG1 in schizophrenia, recent data suggests the possible involvement of NRG1 in ALS." (PMID 26891847, 2016). "In this region, the candidate gene of interest, ‎NRG1, that is involved both in neurodevelopment and neurotransmitter mechanisms in ‎the brain, may play a role in the pathogenesis of schizophrenia." (PMID 27928246, 2016). "However, the future studies are needed to validate the role of the NRG1 selected SNP in schizophrenia and its psychopathology." (PMID 27928246, 2016). "In Nrg1 transmembrane heterozygous knockout mice, pY1472-GluN2B is reduced, in parallel with increased baseline and decreased evoked power of gamma frequency neural oscillations, reproducible features of schizophrenia." (PMID 27134685, 2016). "‎A number of studies have indicated that neuregulin-1 (NRG1) gene may play a role in the ‎pathogenesis of schizophrenia." (PMID 27928246, 2016). "However, it is also possible that primary dysfunction of other genes and signaling molecules, leads to the secondary alteration of NRG1 expression and functioning in schizophrenia." (PMID 27824163, 2016).
schizophrenia (continued). "According to the neurodevelopmental hypothesis for schizophrenia, we established a mouse schizophrenia model by treating neonatal mice with NRG1." (PMID 26935991, 2016). "Low expression of NRG1 mRNA have been found in ‎the brain of patients with schizophrenia." (PMID 27928246, 2016). "A paralog of NRG1, Neuregulin-3 (NRG3) is another risk factor associated with schizophrenia." (PMID 26877878, 2016). "Given that NRG1, ErbB4, and DISC1 are schizophrenia-linked genes, these findings shed light on how independent risk factors may signal in a common developmental pathway that contributes to neural connectivity defects and disease pathogenesis." (PMID 27847649, 2016). "Interestingly, de-regulated neurogenesis is shared by many other generalized candidates for schizophrenia such as Neuregulin (NRG1) and Disrupted-in-schizophrenia 1 (DISC1)." (PMID 27670918, 2016). "While homozygous mice are embryonic lethal, heterozygous KO of NRG1, and its various isoforms display multiple schizophrenia-related behavioral deficits, including impaired PPI and LI, hyperactivity in the OFT, deficits in fear conditioning, impaired working memory, and/or abnormal social behavior." (PMID 25762938, 2015). "Similarly, studies of DISC1 knockout mice and neuregulin 1 (NRG1) knockout mice as models for schizophrenia initially focused on the role these proteins play in neurons, but more recently, their activities in glial cells have begun to be considered." (PMID 26029044, 2015). "A receptor of NRG1, ERBB4 is also associated with schizophrenia." (PMID 25805966, 2015). "We have reanalyzed the association between COMT, ERBB4 or NRG1 and EEM in schizophrenia." (PMID 26242244, 2015). "An example is provided by a SNP of the Neuregulin-1 (NRG-1) gene (X); an imbalance in Neuregulin-1 (NRG-1β) may disrupt the dopaminergic and glutamatergic functions, neurotransmitter pathways associated with schizophrenia." (PMID 26157387, 2015). "Neuregulin-1 and ErbB4 mouse models have been extensively studied for functional and behavioral studies since they show schizophrenia-related behaviors including hyperactivity in the open field, defects in the Prepulse Inhibition (PPI) and deficits in fear conditioning and extinction." (PMID 26733804, 2015). "Moreover, mice with reduced levels of NRG1 or ErbB4 have exhibited behavioral alterations akin to those found in schizophrenia." (PMID 26029044, 2015). "Neuregulin-1 and epidermal growth factor (EGF) are implicated in the pathogenesis of schizophrenia." (PMID 24949465, 2014). "Reduced levels of the expression of NRG1 have also been reported in schizophrenic post-mortem tissues, which indicates that alterations in NRG1 might contribute to the pathophysiology of schizophrenia." (PMID 24782733, 2014). "Along these lines, many groups have reported association of the NRG1 – ERBB4 risk variants with neurocognitive, electrophysiological and neuroimaging schizophrenia-related outcome variables, including altered fronto-temporal brain function and white matter density and integrity." (PMID 24478629, 2014). "Examination of the protective effects of estrogen (i.e., the estrogen protection hypothesis of schizophrenia) in our TMc-Nrg1 mutant mice is warranted." (PMID 24782733, 2014). "EGF and NRG1 have been researched extensively in relation to schizophrenia." (PMID 24949465, 2014). "The variety of functions subserved by NRG in the brain's development suggests the possibility that other SNP or haplotypes related to NRG1 and/or ERBB4 may be associated to cognitive deficit and/or disorganized cortical activity in schizophrenia." (PMID 24976857, 2014). "Other genetic variants related to NRG1 have been associated to schizophrenia, such as the non-synonymous (Arg/Gln) SNP rs3924999." (PMID 24976857, 2014). "Accumulating evidence from human genetic studies suggests that multiple susceptibility genes or loci, including Neuregulin 1 (NRG1), might contribute to the pathogenesis of schizophrenia." (PMID 24782733, 2014).